CDKN2A (cyclin dependent kinase inhibitor 2A)
Diseases named in the same sentence as CDKN2A in open-access papers (continued):
Sharing a sentence is not in itself a finding about the gene and the disease.
tumor (continued). "This implicates that the functional role of genetic risk variants in the 9p21.3 region may not only be through direct regulation of the nearby tumor suppressor genes CDKN2A/B, but also through distant regulatory effects." (PMID 31842352, 2019). "The biological consequence of tumor-suppressor gene inactivation, however, is the erosion of IDH1R132H tumor-suppressive activity, as indicated by the complete loss of IDH1R132H survival benefit in Cdkn2a−/− mice in contrast to Cdkn2a+/+ and Cdkn2a−/+ mice." (PMID 30416682, 2018). "Thus, our work identifies CDKN2A as the first tumor suppressor whose inactivation promotes homotypic CIC formation in human cancer cells." (PMID 29904067, 2018). "Furthermore, promoter methylation of both CDKN2A (p14ARF) and MGMT has been associated with tumour stage and the addition of GSTP1 and TIMP3 promoter methylation allowed to discriminate invasive tumours." (PMID 30149597, 2018). "P16INK4A is encoded by the CDKN2A gene and is thought to be a tumor suppressor." (PMID 30150594, 2018). "The reported overexpression of CDKN2A in genomically unstable tumours could be a sign of an in vain countermeasure to reduce cell cycle activity, which is deregulated due to other molecular aberrations." (PMID 30258198, 2018). "Based on our sequencing data, CCND1 amplification and CDKN2A loss are common mutation signatures for NPC tumor; and we have demonstrated that PAL is an effective drug targeting cell cycle to suppress tumor growth in NPC PDX model with CCND1 and CDKN2A CNV background." (PMID 30236142, 2018). "In addition to data on 1p/19q co-deletion, TERT promoter and IDH mutation, for 1955 of the tumours we had information on EGFR amplification and CDKN2A deletion status." (PMID 29460007, 2018). "An additional distinct, non-synonymous SNV identified in another tumor suppressor gene, CDKN2A, was found to be shared by most of the examined single aneuploid CECs in all the inspected subjects of the same population of patients with diverse carcinomas (our unpublished, ongoing study)." (PMID 29670052, 2018). "Importantly, when injected subcutaneously into female SCID-beige mice, shRNA-Tsc2/Cdkn2a∆/∆ (n = 12 injections) and shRNA-Tsc2 + Cdkn2a (n = 16 injections) sphere-selected cells formed slowly growing tumours within 1–2 months." (PMID 29133867, 2017). "The finding that mutations in CDKN2A cause Sex-linked barring in chickens was unexpected as it is an important tumor suppressor gene that had not previously been associated with pigmentation phenotypes in any species." (PMID 28388616, 2017). "Adjacent tumour suppressor pairs (e.g., CDKN2A/CDKN2B, BIRC2/BIRC3, HELQ/FAM175A...) may be especially rewarding targets for homozygous deletion in some cases, as two mutation events can abolish all tumour suppressor activity." (PMID 29089486, 2017).
tumor (continued). "However, exon 2 of CDKN2A more frequently showed a methylation status ≥ LOQ in tumor (94%, 17/18) than in tumor-adjacent (50%, 9/18) and tumor-distant (56%, 10/18) tissues." (PMID 28403857, 2017). "In addition, tumor-adjacent (p = 0.002) and tumor-distant tissues (p = 0.005) showed significantly higher methylation levels of CDKN2A exon 2 than normal breast tissues serving as control." (PMID 28403857, 2017). "Immunostaining with epithelioid MPNST marker, S100β, showed strong expression in spindle-shaped tumor cells (2D’) while the mesenchymal marker, Vimentin, also showed extensive staining in tumor tissues of cdkn2a/b TALEN mRNA injected tp53e7/e7 mutant zebrafish (2E’)." (PMID 28903419, 2017). "WES analysis of this tumor and matching blood revealed amplification of chromosome 7 and deletion of chromosome 10, together with focal deletion of the cyclin-dependent kinase inhibitor 2A (CDKN2A) locus on chromosome 9." (PMID 28153049, 2017). "We next examined whether human ccRCC tumours with similar genomic characteristics (VHL inactivation; VHL inactivation and MYC activation; and VHL inactivation, CDKN2A loss and MYC activation) have similar outcomes as those seen in our mouse models." (PMID 28593993, 2017). "To check whether ZEB1 binds and represses CDKN1A and CDKN2A genes in human tumor cells, we conducted ChIP assays and found that ZEB1 was indeed bound to CDKN1A promoter, implying a direct regulatory role for ZEB1 to promote cell proliferation in UM cells." (PMID 28246385, 2017). "Corroborating these correlations, in our cohort of invasive corticotrophinomas, with underexpression of CDKN2A, the mean tumor size was significantly higher (27.7 ± 11.2 mm) than in the non-invasive corticotrophinomas (10.9 ± 4.8 mm), even when we consider only the size of MACs (15.40 ± 4.04 mm)." (PMID 28382019, 2017). "CDKN2A (9%), FAT1 (23%), SMAD4 (11%), and CASP8 (13%) mutations were only present in HPV-negative HNSCC cell lines, which was consistent with the HNSCC TCGA data, where each of these mutations occurred in only 1 HPV-positive HNSCC patient tumor." (PMID 29156801, 2017). "In summary, we showed that PLGG tumorigenicity was low despite the presence of putative CSCs, and our data supported GFAP−/Vimentin+ cells, CDKN2A homozygous deletion in trisomy chromosome 9 cells, and BRAF V600E mutation as candidate drivers of tumor progression in the PXA xenografts." (PMID 29152094, 2017). "For the following genes, a correlation was found between the methylation levels in tumors and those in tumor-adjacent tissues: CDKN2A (promoter) (r = 0.927, p < 0.001); BRCA1 (r = 0.878, p < 0.001); APC (r = 0.706, p = 0.001), ESR1 (r = 0.545, p = 0.019) and ESR2 (r = 0.543, p = 0.024)." (PMID 28403857, 2017). "Cultured xenograft tumor cells also maintained the homozygous CDKN2A deletion." (PMID 29152094, 2017). "To explore whether disruption of Cdkn2a occurred prior to tumor development, we examined the status of Cdkn2a in laser-dissected mesothelial cells from advanced inflammatory lesions." (PMID 29112861, 2017). "CDKN2A is a tumor suppressor acting via INK4a/p16 and ARF/p14 proteins." (PMID 28580304, 2017). "Indeed, loss of the p16 and ARF-encoding CDKN2A gene was observed in around half of all gliomas, possibly contributing to autophagic cell death aversion during growth of the tumor." (PMID 28459042, 2017). "We observed that cyclin-dependent kinase inhibitor gene CDKN2A rs3088440 was significantly related with a poorer treatment efficacy on the primary tumor and cervical lymph node after radiotherapy, and also with a decreased risk of grade 3–4 acute radiation-induced myelosuppression." (PMID 28445979, 2017).
tumor (continued). "Likewise, as a tumor suppressor gene, CDKN2A played an important control role in cell cycle regulating during the G1 phase." (PMID 28977860, 2017). "Interestingly, a high transcript level of CDKN2A was consistently observed in all the tumor cell lines with CDK4 amplification and high levels of CDK4 transcript reported in Cosmic database." (PMID 28566333, 2017). "LOH within CDKN2A region was detected and agreed upon by both the techniques in 6 tumours." (PMID 27682877, 2016). "Various experiments revealed that paboxilin inhibited cell growth or mice tumor proliferation with CDKN2A deletion selectively and sensitively, which indicated that CDKN2A/B CNL may respond to CDK4/6 inhibitor." (PMID 27974690, 2016). "Additionally this tumour contained a deletion surrounding CDKN2A/B, and an amplification of the RAS-related oncogene RAB14 on chr9q33.2." (PMID 27843499, 2016). "It is well known that accelerated tumor cell proliferation could occur as a result of CDKN2A/B deletion due to the direct removal of tumor suppressors and activation of tumor growth factors such as MDM2 and CDK4/6." (PMID 27090891, 2016). "In addition to CDKN2A, a number of well-established tumour suppressors and oncogenes were identified as potentially regulated by asRNA." (PMID 29263803, 2016). "These two mechanisms could be involved in tumour progression if they result in inactivation of tumour suppressor genes, such as CDKN2A/B located on chromosome 9p." (PMID 27682877, 2016). "Studies on oesophageal cancer have shown that copy number neutral LOH is a common phenomenon The literature contains few reports on CNN-LOH in clear cell RCC especially in the region of chromosome 9p21, which harbours CDKN2A/B, one of the main tumour suppressor genes." (PMID 27682877, 2016). "However, one of the focal SCNAs involved a gene with strong a priori importance in cancer, this being a deletion of ~1 Mb around CDKN2A in tumour P02." (PMID 25790038, 2015). "We too observed the acquisition of biallelic deletion of CDKN2A (a reflection of tumor progression) in the nodal metastasis of at least 2 patients in whom the primary tumors retained both copies of the gene, but neither patient developed extranodal metastasis in follow-up." (PMID 26061100, 2015). "We observed a strong association between somatic variations in some key genes with one or more risk habits; for example,CDKN2A andPIK3CA with smoking;CASP8 with consuming alcohol and chewing tobacco;RASA1 with chewing and tumor stage, and HPV infection, along withDMD andPIK3CA." (PMID 26834999, 2015). "Notably, our interaction network analysis of miRNA-overtargeted genes showed that miR-320 is involved in several interactions that target important tumor suppressor genes such as CDKN2A and PTEN." (PMID 26057471, 2015). "Therefore, the selective pressure during the initial hyperdiploid event would be less than that for SNPs within regions of secondary tumor alterations, such as deletions of CDKN2A and IKZF1." (PMID 26575185, 2015). "P16INK4a was present in all HPV-positive cases; however, lack of p16INK4a immunostaining in HPV-associated tumours due to loss of heterozygosity near the CDKN2A locus and/or hypermethylation of the CDKN2A promoter has been described previously." (PMID 25885064, 2015).
tumor (continued). "This supported the idea that alteration of TGF-β molecular and cellular response may be influenced by cdkn2a locus inactivation during tumor development." (PMID 26078812, 2015). "Therefore, the changes in DNA methylation observed within the downstream CpG island of the CDKN2A locus are correlated with a tumor-specific increase in p14(ARF) mRNA expression." (PMID 25619363, 2015). "Earlier report showed that miR-31 is located at the chromosome 9q21.3, and this locus is very close to the locations of tumor suppressors, CDKN2A and CDKN2B, that is frequently deleted in many cases of cancers, which may result in down-regulation of miR-31." (PMID 25797269, 2015). "The second tumor suppressor gene is CDKN2A, which encodes two proteins, p16INK4A and p14ARF." (PMID 26634163, 2015). "The two remaining tumor samples completely matched with their primary cultures for their CDKN2A deletion status, further confirming that primary cells obtained from patient’s malignant effusions have the same genetic alterations as in the corresponding primary human tumor." (PMID 25952750, 2015). "The tumor unexpectedly contained a BRAF V600E mutation, CDKN2A loss and PTPRD S1845fs*2 mutation." (PMID 25563358, 2014). "The alterations found in this tumor were the BRAFV600E mutation, CDKN2A loss and PTPRD S1845fs*2." (PMID 25563358, 2014). "Here, we report that in the absence of Cdkn2a, Ptprd loss results in accelerated tumor development compared to mice lacking Cdkn2a alone." (PMID 25138050, 2014). "p16 (also known as CDKN2A) is a well-established tumor suppressor." (PMID 25598836, 2014). "We will now describe in detail three notable genes from this category for which differential isoform usage may play a role in tumor development and growth: CDKN2A, FAM64A and KLK12." (PMID 25030904, 2014). "In order to determine why mice with Ptprd loss had a faster onset of clinical signs, we first examined whether mice with Ptprd and Cdkn2a deletion had a greater number of tumor types compared to mice with Cdkn2a deletion alone." (PMID 25138050, 2014). "For CDKN2A and APC, the mutation proportions were initially (in tumor samples) strongly shifted towards nonsense homozygous; however, the increase of this mutational type with the subsequent decrease of the other types of mutations was statistically significant." (PMID 25119593, 2014). "Tumours of CDKN2A mutated patients had significantly more big round cells than tumours of non-carriers (35.3% vs 4.7%), p<0.05." (PMID 25893138, 2014). "Our approach was based on the results for the known tumor suppressors CDKN2A and PTEN." (PMID 24670534, 2014). "There was also some weak evidence that thinner tumours were associated with CDKN2A mutations for the UK samples (p = 0.05, data not shown), but not for the Australian or Spanish samples." (PMID 25780468, 2014). "This region encodes the CDKN2A and CDKN2B tumor suppressor genes, and may be deleted in several tumor types." (PMID 25314013, 2014). "The different metastatic behavior of RMSp53Neu-1 and RMSp53Neu-5 after CDKN2A silencing might refect tumor heterogeneity, and suggest the need of further studies to test the role of CDKN2A as a therapeutic target." (PMID 24334679, 2014). "However, as well as functioning as a tumour suppressor, CDKN2A is also a component of stress-induced premature senescence (SIPS) which prevents T-cell replication following acute insult." (PMID 23994067, 2013).
tumor (continued). "Moreover, a survey of prior gene expression profiling studies in Oncomine suggested a correlation between elevated CDKN2A mRNA levels and increased tumor grade." (PMID 23894465, 2013). "Within the INK4b-ARF-INK4a locus at human chromosome 9p21, CDKN2A encodes two potent tumor suppressors, p16INK4a, and p14ARF (p19ARF in mice); these proteins are critical negative regulators of cell proliferation." (PMID 24167519, 2013). "Most critically, somatic deletion of the potent tumor-suppressor CDKN2A was identified." (PMID 23653877, 2013). "Additionally, some other loci showing significant differences in DNA methylation levels between tumor and non-tumor lung tissue have been identified, including: CDKN2A EX2, CDX2, HOXA1, SFPR1, and TWIST1 gene." (PMID 23086271, 2013). "Frag_01, Frag_02 and ZIC4 present a much lower P-value, indicating they may be better tumor markers than CDKN2A and RASSF1." (PMID 22726460, 2012). "In addition, CDKN2A amplification with the M primer was often observed in lung tissue samples, although at much lower amplification levels when compared with tumor samples." (PMID 22726460, 2012). "In this scenario CDKN2A loss is coupled to tumor progression rather than initiation, perhaps by further promoting a CCND1 driven activation of the cell cycle G1 phase of the cell cycle." (PMID 22685613, 2012). "The loss of one SUZ12 allele in patients with germline NF1 microdeletions may well influence ANRIL-mediated expression regulation of the CDKN2A/CDKN2B tumour suppressor genes." (PMID 23101500, 2012). "The CpG island of CDKN2A gene is more frequently methylated in fresh tumor cells isolated from patients with acute ATL (47%) or lymphoma type ATL (73%) than in fresh tumor cells isolated from patients with chronic (17%) and smoldering (17%) ATL, which are relatively less malignant." (PMID 23060864, 2012). "The other CDKN2A product, p16INK4A, also suppresses tumors, and is itself suppressed in neoplasms." (PMID 22829758, 2012). "Given the high predictive accuracy and quantitative nature of the CCND1/CDKN2A expression assay, the assay could be utilized to stratify patients for anti-tumor agents with preferential effects on either RB1-positive or -negative tumors." (PMID 21447152, 2011). "Finally, CCND1/CDKN2A expressions were measured in formalin fixed paraffin embedded (FFPE) samples of clinical tumor and normal tissues." (PMID 21447152, 2011). "Notably, many of the qPCR-ratios obtained for Cdkn2a and Nf1 were consistent with losses throughout the tumor." (PMID 21533183, 2011). "The CDKN2A gene was frequently methylated in tumor tissue (77%)." (PMID 22547956, 2011). "The ARF/CDKN2A/B proteins are established tumour suppressors deleted in a range of cancers including familial cutaneous malignant melanoma; they block cell cycle progression and influence key physiological processes such as replicative senescence, apoptosis, and stem-cell self-renewal." (PMID 20386740, 2010). "Kamb examined 290 tumor cell lines and detected CDKN2A deletion in 133 of them." (PMID 20565749, 2010). "Although it has been speculated that this change in intra-cellular localization within tumor buds may be due to promoter methylation of CDKN2A, the role of p16 in tumor budding in both MSS and MSI-H colorectal cancers needs further clarification." (PMID 21317460, 2010). "In concurrence with these findings, Myc insertions were identified in 20% of tumours from MuLV-infected Cdkn2a (Ink4a/Arf)-deficient mice, but none contained insertions in Bmi1." (PMID 19285540, 2009).